IL4 (interleukin 4)
Diseases named in the same sentence as IL4 in open-access papers (continued):
Sharing a sentence is not in itself a finding about the gene and the disease.
age-related macular degeneration (5 papers, 2020 to 2025). Age-related loss of vision in the central portion of the retina (macula), secondary to retinal degeneration. "Association of IL-4 concentration in aqueous humor with subtype of age-related macular degeneration." (PMID 32366355, 2020). "For instance, inflammatory IFN-γ-stimulated macrophages, particularly from patients with age-related macular degeneration, show typical M1-like characteristics and are markedly pro-angiogenic, even more than IL-4-stimulated macrophages." (PMID 40429986, 2025). "Increase of IL-4 concentration in aqueous humor of eyes with age-related macular degeneration." (PMID 32366355, 2020).
atrial fibrillation (5 papers, 2018 to 2025). A disorder characterized by an electrocardiographic finding of a supraventricular arrhythmia characterized by the replacement of consistent P waves by rapid oscillations or fibrillatory waves that vary in size, shape and timing and are accompanied by an irregular ventricular response. "Compared with that in the control group, the level of interleukin-4 in patients with atrial fibrillation-related thrombosis, arterial thrombosis, or major bleeding increased by 53-fold (0.53 vs. 0.01 pg/ml), 17-fold (0.17 vs. 0.01 pg/ml), and 19-fold (0.19 vs. 0.01 pg/ml), respectively." (PMID 36211709, 2022). "Plasma levels of inflammatory cytokines of IL‐2, IL‐4, IL‐10, TNF, and IFN‐γ were reduced upon rivaroxaban treatment compared to warfarin in atrial fibrillation patients, with levels still slightly higher than controls." (PMID 40292918, 2025). "Elevated levels of CXCL8, CCL11, CCL2, CXCL10, IL-1β, IL-6, TNF-α, IFN-γ, IL-17, IL-1Ra, IL-4, IL-9, FGF-basic, PDGF, G-CSF, and GM-CSF were observed in the Atrial fibrillation patient, in contrast to uninfected controls." (PMID 29370812, 2018).
autoimmune encephalitis (5 papers, 2012 to 2023). Inflammation of the brain secondary to an immune response triggered by the body itself. "Similarly, in experimental autoimmune encephalitis models, externally administered IL-4 has been shown to improve axonal damage via IL-4 receptor (IL-4R)-mediated signaling pathway." (PMID 33504893, 2021). "In rats with experimental autoimmune encephalitis, unlike in the peak of disease progression, IL-4 can be identified in the brain tissue from rats that are naturally recovering from the disease, suggesting the regulatory role of IL-4 in disease remission." (PMID 29184551, 2017). "However, Th2 T cells produce IL-4, 6, 10, and 13, most activated by our EB101 vaccine in APPswe/PS1dE9 transgenic mice and believed to help humoral immunity, essential for helping antibody production and suppression of autoimmune encephalitis." (PMID 23024882, 2012).
brain inflammation (5 papers, 2007 to 2024). "Since IL-4 induces apoptosis in activated glial cells that express IL-4R, IL-4 may contribute to the down-regulation of brain inflammation in CM-R mice." (PMID 18062806, 2007). "Our findings revealed that the serum levels of IL-4, IFN-α, IFN-γ, IL-6, TNF-α, CCL4, P-cadherin, TRAIL, CCL11, and VEGF were significantly higher in cases of brain inflammation compared with brain gliomas." (PMID 39364412, 2024). "In animal models of inflammatory brain disease such as EAE, microglial cells have been proved to be an important source of IL-4, suggesting that factors present in the CNS microenvironment (absent in the culture system) are essential for production of this cytokine." (PMID 27359332, 2016).
Burkitt lymphoma (5 papers, 2005 to 2023). A rare form of malignant mature B-cell non-Hodgkin lymphoma. "Similarly, pentagalloylglucose and tannic acid impaired IL-4/STAT6 signaling in Burkitt lymphoma cells." (PMID 36012541, 2022). "Only in Burkitt's lymphoma, in three of 35 malignant B-samples, and in human head and neck squamous cell carcinoma cells, IL-4 was reported to stimulate cell proliferation." (PMID 15714203, 2005).
cardiomyopathy (5 papers, 2018 to 2024). A disease of the heart muscle or myocardium proper. "It is possible in our study that eosinophils lead to inflammatory mediated cardiomyopathy via upregulation of IL-4, which was increased in terms of gene expression in the hearts of hamsters on day 8 post SARS-CoV-2 inoculation." (PMID 34265022, 2021). "Among studied cytokines, some were associated with general susceptibility to T. cruzi infection (IFN-γ, MIF, IL-4, TNF, TGF-β, and IL-18) and others with cardiomyopathy development (TNF, IL-1, BAT1, MCP-1, LT-α, IL-12, and IL-10)." (PMID 29670670, 2018). "Moreover, other SNP related to other cytokines that could be related to susceptibility to T. cruzi infection (IFN-γ, MIF, IL-4, TNF, TGF-β, and IL-18) or cardiomyopathy development (TNF, IL-1, BAT1, MCP-1, LT-α, IL-12, and IL-10) were not studied." (PMID 29670670, 2018).
Chlamydia infection (5 papers, 2008 to 2025). "The present study showed that Chlamydia infection causes respiratory distress in early life and suppresses the IL-4 alpha thereby enabling the IL-4 to promote infection." (PMID 34226412, 2021). "This IL-4-mediated enhancement of immune responses also triggers delayed type hypersensitivity (DTH) during Chlamydia infection, which might be associated with asthma due to Chlamydia." (PMID 34093528, 2021). "An excessive Th2-type response can impair host resistance to intracellular Chlamydia infection, prompting us to examine IL-4, a key driver of Th2 differentiation, and evaluate its role in ccr2-/- mice." (PMID 39903705, 2025). "Conversely, our findings reveal that CCR2 deficiency leads to excessive Th2-type immune responses, characterized by increased production of IL-4 and IL-5, which compromise the host’s ability to effectively combat intracellular Chlamydia infections." (PMID 39903705, 2025). "IL-4 can be detected in the culture supernatant of PBMCs isolated from patients with Chlamydia infection." (PMID 34093528, 2021). "In fact, IL-4 is produced primarily by Th2 cells upon Chlamydia infection in adults." (PMID 34226412, 2021). "However, STAT6-/- mice were vulnerable to Chlamydia infection, thus revealing that IL-4-mediated STAT6 signaling pathway triggered and induced the infection." (PMID 34226412, 2021). "Based on these data, strongly expressed IL-4 could inhibit Chlamydia infection to a certain extent, and also effectively prevent tissue damage." (PMID 34093528, 2021). "Therefore, IL-4 is considered to play a role in Chlamydia infections." (PMID 34093528, 2021). "Moreover, during Chlamydia infection, IL-4 is necessary for Th2 cell differentiation." (PMID 34226412, 2021). "Since cellular immunity is a key component of the protective immune response following Chlamydia infection, we evaluated the magnitude of Th1 (IFN-γ, IL-2, IL-12, IL-18), Th2 (IL-4) and anti-inflammatory (IL-10) cytokines (Expt." (PMID 34001988, 2021). "However, the role of IL-4 in Chlamydia infection has not been adequately investigated and further elucidation is necessary." (PMID 34093528, 2021).
chronic pancreatitis (5 papers, 2009 to 2026). A chronic inflammatory process causing damage and fibrosis of the pancreatic parenchyma. "Here the authors use a mouse model of chronic pancreatitis to show that Treg cells reduce IL-4 mediated chronic inflammation in the pancreas associated with M2-like macrophages in vivo." (PMID 35922425, 2022). "To investigate the effect of IL-4 during chronic pancreatitis, we treated C57Bl/6 mice with an IL-4 neutralizing antibody, whereas control animals received isotype antibody in the same treatment scheme." (PMID 35922425, 2022). "It has been observed in several experimental models that IL-4 could modulate the regulation of complement activation or the generation of IL-10 in chronic pancreatitis." (PMID 19646232, 2009). "Our study demonstrates that the IL-4/IL-13 STAT6-signaling pathway represents a critical regulatory mechanism suppressing the inflammation and stimulating wound healing and organ regeneration during acute and chronic pancreatitis." (PMID 41486955, 2026).
colorectal tumors (5 papers, 2012 to 2022). "After treatment with ZQFZ, the proportion of CD4- and CD8-positive cells in the spleen and colorectal tumors of ApcMin/+ mice increased significantly and the proportions of IFN-γ- and IL-4-expressing cells were also altered." (PMID 35680568, 2022). "A recentstudy showed that the levels of IFN-γ mRNAwere higher in colorectal tumor specimens thannormal tissues, but not for IL-4 mRNA." (PMID 23507624, 2012).
cutaneous T-cell lymphoma (5 papers, 2021 to 2025). "The interleukins IL-4 and IL-13 are increasingly recognized contributors to the pathogenesis of cutaneous T cell lymphomas (CTCLs), and their role in disease-associated pruritus is accepted." (PMID 38398754, 2024). "A further layer of complexity is added by the positive feedback between NLRP3 and the IL-4 promoter, particularly in malignant CD4+ T cells of cutaneous T cell lymphoma, which perpetuates high IL-4 production and reinforces the Th2-dominant, immunosuppressive environment." (PMID 40864740, 2025). "The finding of a statistically significant association between Dupilumab use and progression/exacerbation of cutaneous T-cell lymphoma may sound surprising and contradict the literature, in that IL4 and IL13 are overexpressed in this malignancy and their dual suppression should inhibit the tumor." (PMID 37954855, 2023).
Dengue hemorrhagic fever (5 papers, 2013 to 2021). A serious condition caused by Dengue virus infection. "The increase in plasma expression of Th2 cytokines (i.e., IL-4, IL-13) may be associated with augmentation of vascular permeability and vascular leakage as seen in dengue haemorrhagic fever." (PMID 26271921, 2015). "IL-4, was shown to be also increased in patients with Dengue hemorrhagic fever." (PMID 31357521, 2019). "Increased levels of TNF-α, IL-1β, IL-4, IL-6, IL-8, IL-13, IL-15, macrophage migration inhibitory factor (MIF), and chemokines CCL2, CCL4, CCL5, and CXCL10 (IP-10) among others, have been reported in patients with dengue hemorrhagic fever (DHF) when compared to dengue fever (DF)." (PMID 29986388, 2018).
dry eye (5 papers, 2015 to 2024). "Increases of IFN-γ, IL-2, IL-4, IL-5, IL-13 or IL-β1 in SAC; TSLP in both PAC and SAC; and IL-17, IL-21 and IL-22 in dry eyes have been observed in different studies." (PMID 35935953, 2022).
glomerulonephritis (5 papers, 2011 to 2021). A renal disorder characterized by damage in the glomeruli. "Depletion of basophils limits IL-4 production, reduces IgE, reverses the Th2 bias in these animals and improves the characteristic glomerulonephritis, caused by antibody complex deposition." (PMID 29619025, 2018). "Immune modulation with IL-4 and IL-10 prevented crescent formation and glomerular injury in experimental glomerulonephritis." (PMID 34205404, 2021). "Systemic atopic expression of IL-4 resulted in the development of autoimmune-like disorders, including autoimmune hemolytic anemia, glomerulonephritis, and Ig deposits in the kidney, which were primarily mediated by elevated levels of autoantibodies." (PMID 29184551, 2017). "Glomerular IL-4 mRNA increased markedly 16 hours post-nephrotoxic serum injection, and was then reduced, suggesting a potential role for T cell-derived IL-4 in directing the expression of 12/15-LO during glomerulonephritis." (PMID 21569625, 2011).
HCMV infection (5 papers, 2012 to 2024). "This study has also shown that enumeration of IFN-γ and IL-4 SFCs may discriminate aGVHD from CMV infections." (PMID 24710414, 2012). "This is interesting because HCMV infection seemed to lead to lower pro-inflammatory (TNF, IL1β, eotaxin, GMCSF) and Th2 (IL-4) reactivity to general T cell stimulation and the mycobacterial antigen PPD as compared to the HCMV- infants." (PMID 32582177, 2020). "CMV infection is able to trigger IFN-γ and IL-4 response and elicit potent memory responses in chronically infected immunocompetent hosts." (PMID 24710414, 2012). "Elevation of IFN-γ and IL-4 SFCs was significantly correlated with the severity of aGVHD, but not with infection itself, e.g., cytomegalovirus infection." (PMID 24710414, 2012). "Thus, IFN-α expression by SmyleDC and SmyleDCpp65 controlled HCMV infection and release, whereas IL-4 expression by SmartDC did not." (PMID 26052526, 2015). "In the current study, we could not detect the elevation of IFN-γ and IL-4 SFCs in patients with CMV infection without aGVHD." (PMID 24710414, 2012).
head and neck squamous cell carcinoma (5 papers, 2005 to 2025). A squamous cell carcinoma that arises from any of the following anatomic sites: lip and oral cavity, nasal cavity, paranasal sinuses, pharynx, larynx, and salivary glands. "Growth of cancer cells is induced by IL-4 via paracrine mechanisms, and the expression of IL-4 has been reported in head and neck squamous cell carcinoma and OSCC." (PMID 28053372, 2016).
hemorrhage (5 papers, 2013 to 2021). Loss of blood from the vascular compartment to the exterior or into nonvascular body space as a result of rupture or severance of the blood vessels. "The contents of IL-2, IL-4 and TIPE2 produced by splenic CD4+ T lymphocytes were decreased following trauma-hemorrhage, which were normalized by administrations of E2 or PPT, but not DPN or G1." (PMID 33820957, 2021). "Relative to levels of the pre-hemorrhage (0 min), the plasma levels of IL-4 were not significantly increased, while IL-10 was significantly increased at 90 and 180 min (by about 1.5 and twofold) post-REBOA in the 25 min REBOA + TRIC37°C group." (PMID 34211011, 2021).
hyperreactivity (5 papers, 2010 to 2024). "In this study, treatment with anti‐S100A4 antibody significantly inhibited Th2-mediated airway hyperreactivity and reduced the production of IL-4 and IL-13." (PMID 37873538, 2023). "The constituents of the plant also showed inhibitory effects on IL-4 production, IgE formation, mast cell and basophil degranulation, histamine secretion and airway hyperreactivity as well as improvement of Th1/Th2 balance and anti-allergic effects." (PMID 34567150, 2021). "In addition, TIM-1 facilitated pulmonary iNKT cells to bind rather than engulf apoptotic cells as a typical PS receptor, which enhanced iNKT cell production of IFN-γ and IL-4 and subsequent initiation of airway hyperreactivity." (PMID 27662666, 2016).
Listeria monocytogenes infection (5 papers, 2012 to 2016). "Similarly, during Listeria monocytogenes infection, hepatocyte derived IL‐33 was found to increase macrophage proliferation in the liver 16, and assumed to be due to an amplification loop acting via basophil production of IL‐4." (PMID 27592711, 2016).
mammary adenocarcinomas (5 papers, 2015 to 2021). "DeNardo and coworkers showed that mice treated with murine IL-4 neutralizing antibodies exhibited decreased numbers of metastatic foci in the lungs and overall attenuation of total pulmonary metastasis of mammary adenocarcinomas." (PMID 33804263, 2021). "We used a multivariate principal component analysis applied to analyze the joint behavior of serum concentrations of IFN-γ, IL-2, IL-10 and IL-4, during the different phases of tumor immunoediting, in CBi/L mice challenged with M-406 mammary adenocarcinoma." (PMID 33312693, 2020). "The complex interplay between T cells and the humoral immune system was demonstrated in the MMTV-PyMT mouse model, where IL-4-expressing CD4 + T lymphocytes indirectly promote invasion and subsequent metastasis of mammary adenocarcinomas." (PMID 29350274, 2018).
mucositis (5 papers, 2012 to 2022). Mucositis is inflammation and damage of the mucous membranes lining the mouth and other parts of the gastrointestinal (GI) tract. "There remains, however, a huge gap in the knowledge to recognise whether anti-inflammatory cytokines such as IL-4, IL-10, IL-11, and IL-1ra are essential tools in downregulating the inflammatory response associated with mucositis." (PMID 22973511, 2012). "Although evidence suggests that IL-4 has potential anti-inflammatory effects, its role during mucositis remains undefined." (PMID 22973511, 2012). "Thus it is obligatory for forthcoming studies to address these issues in order to develop better understanding of the anti-inflammatory properties of IL-4 during inflammation in mucositis." (PMID 22973511, 2012).
myasthenia gravis (5 papers, 2018 to 2024). Myasthenia gravis (MG) is a rare, clinically heterogeneous, autoimmune disorder of the neuromuscular junction characterized by fatigable weakness of voluntary muscles. "Interleukin-4 (IL-4) is a potent growth and differentiation factor for B cells which play a vital role in the pathogenesis of myasthenia gravis (MG)." (PMID 30042722, 2018). "The primary endpoints are quantitative myasthenia gravis (QMG) test; measurement of the amount of Treg cells and cytokines such as interferon-γ (IFN-γ), interleukin-4 (IL-4), interleukin-17A (IL-17A), and transforming growth factor-β (TGF-β); and corticosteroid or immunosuppressive agent dosage." (PMID 33371107, 2020).
mycosis fungoides (5 papers, 2019 to 2025). Classical mycosis fungoides is the most common type of mycosis fungoides (MF), a form of cutaneous T-cell lymphoma, and is characterized by slow progression from patches to more infiltrated plaques and eventually to tumors. "This study presents a theoretical framework for combining IL-4 pathway inhibition with Brentuximab Vedotin in the treatment of CD30-positive mycosis fungoides, but several limitations must be acknowledged." (PMID 40864740, 2025). "Despite the biologically supported case for combining IL-4 inhibition with Brentuximab Vedotin in mycosis fungoides, its clinical translation is currently hindered by several critical knowledge gaps." (PMID 40864740, 2025). "Blocking IL-4/IL-13 signaling pathways by anti-IL-4 neutralizing antibody reduces the proliferation of mycosis fungoides (MF) cells." (PMID 39758935, 2025). "The interaction between IL-4 signaling and Brentuximab Vedotin’s efficacy in mycosis fungoides (MF) reflects a convergence of tumor immunobiology and targeted therapy." (PMID 40864740, 2025). "This review analyzes current knowledge on the IL-4/IL-13 axis in mycosis fungoides and Sezary syndrome, the most common types of CTCL, examining existing literature on the pathogenetic implications with a focus on investigational treatments." (PMID 38398754, 2024). "For example, the production of IL-4 is increased in the cancer stroma of the advanced stage compared to the early stage in mycosis fungoides, leading to an increased ratio of CD163+CD206+ M2 polarized TAMs, which could be a measure of the transition to the advanced stage." (PMID 35409404, 2022). "The convergence of IL-4 signaling and Brentuximab Vedotin (BV) therapy in CD30-positive mycosis fungoides presents a compelling but as yet unvalidated therapeutic hypothesis." (PMID 40864740, 2025). "Notably, CD163+CD206+ TAMs produce M2 macrophage-related chemokines such as CCL22 by the stimulation of IL-4 in cancer stroma, which leads to recruitment of CCR4+ lymphoma cells to develop tumor formation in mycosis fungoides." (PMID 35409404, 2022).
neuroblastoma (5 papers, 2015 to 2024). Neuroblastoma (NB) is the most common solid, extracranial childhood tumor. "It is worth noting that the NMB-NMBR axis can mediate the release of chemokines, such as IL-4 in the intestine, IL-8 in neuroblastoma, and VEGF in tumor." (PMID 39214988, 2024). "We think the long-lasting ROS production in IL-4-treated microglia (elevated for at least 2 days) is likely mediated by mitochondria, because PKG is known to stimulate mitochondrial ROS production in cardiomyocytes and a neuroblastoma cell line." (PMID 25904916, 2015).